OR1P1 (olfactory receptor family 1 subfamily P member 1 (gene/pseudogene))
Description:
Odorant receptor.
Synonyms: OR17-208; OR1P1P
Gene: Protein-coding gene on chromosome 17 (3,153,889 to 3,154,882, reverse strand). Ensembl gene ENSG00000262085.
Subcellular location: Cell membrane
Pathways (Reactome):
Sensory Perception: Expression and translocation of olfactory receptors
Homologues: Orthologues: chimpanzee OR1P1 (95% identical), dog OR1P1 (81% identical), mouse Or1p1 (79% identical), rat Or1p1 (79% identical), mouse Or1p1c (78% identical), rabbit OR1P1 (78% identical), rat Or1p1e (78% identical), mouse Or1p1b (77% identical), guinea pig OR1P1 (72% identical), mouse Or1p4 (38% identical). Paralogues in human: OR1N1 (53% identical), OR1E1 (51% identical), OR1E2 (50% identical), OR1G1 (50% identical), OR1J4 (50% identical), OR7A5 (50% identical), OR7C1 (50% identical), OR1J2 (49% identical), OR7E24 (49% identical), OR1S1 (49% identical), OR7C2 (49% identical), OR1M1 (48% identical), and 116 more.